PLOD2 (procollagen-lysine,2-oxoglutarate 5-dioxygenase 2)
Diseases named in the same sentence as PLOD2 in open-access papers (continued):
Sharing a sentence is not in itself a finding about the gene and the disease.
glioma (continued). "Our investigation provides evidence that inhibition of PLOD2 attenuates glioma cell migration and invasion both in vitro and in vivo via the modulation of PI3K/AKT signaling pathway and promotion of EMT." (PMID 28410212, 2017). "Clinical data revealed that expression of PLOD2 was significantly correlated with the status of pathology classification in human glioma." (PMID 28410212, 2017). "Knockdown of PLOD2 in glioma cell lines led to decreases in migration and invasion under normoxia and hypoxia." (PMID 28423580, 2017). "Here, this study provides the first piece of evidence that PLOD2 is involved in hypoxia-induced EMT in glioma cells." (PMID 28410212, 2017). "Chi-square test showed that the levels of PLOD2 protein significantly correlated with the status of pathology classification (WHO I–II vs. III–IV) in 125 glioma patients (P = 0.011)." (PMID 28410212, 2017). "We also performed in vivo studies to assess the potential effects of PLOD2 on glioma invasion within the brain environment." (PMID 28423580, 2017). "Consistently, the immunohistochemistry analysis of 45 glioma tissues also showed a positive correlation between PLOD2 and HIF-1α." (PMID 28410212, 2017). "In this study, we investigated the biological functions of PLOD2 in the development and progression of glioma." (PMID 28410212, 2017). "The role of HIF-1α in the regulation of PLOD2 was further investigated through exposure of glioma cells to the HIF-1α inhibitor PX-478." (PMID 28423580, 2017). "Prominent PLOD2 staining was found in 74 of 125 patients with glioma while prominent HIF-1α staining was found in 76 of 125 patients." (PMID 28410212, 2017). "Taken together, our data suggested that inhibition of PLOD2 attenuates glioma cell proliferation, migration and invasion through modulating multiple EMT-associated factors via PI3K/AKT signaling." (PMID 28410212, 2017). "Taken together, these results indicated that PLOD2 expression induced under hypoxia in glioma cells was mediated by HIF-1α." (PMID 28423580, 2017). "Our data confirmed that silenced expression of HIF-1α lad to markedly suppressed PLOD2 expression in glioma cells under hypoxia." (PMID 28410212, 2017). "Here, PLOD2 was confirmed to be frequently up-regulated in glioma by qRT-PCR, western blot and immunohistochemistry analyses." (PMID 28410212, 2017). "In summary, we demonstrate for the first time that knockdown of endogenous PLOD2 suppresses glioma cell proliferation, migration and invasion through modulating multiple EMT-associated factors via inactivation of PI3K/AKT signaling." (PMID 28410212, 2017). "We additionally found that PLOD2 promoted the release of ECM-degrading MMP2—a mechanism associated with enhanced invasiveness and worse outcomes in different types of cancer, including glioma." (PMID 35682709, 2022). "PLOD2 knockdown inhibited glioma cell proliferation, migration and invasion." (PMID 34421605, 2021). "The anti-angiogenesis effect of PLOD3 may depend on disarrangement of collagen alignment in glioma, which has been observed in an in vivo xenograft study with knockdown of PLOD2, the other PLOD3 isoform." (PMID 29644003, 2018). "Recent study also reveal that PLOD2 expression induces PI3K/AKT signaling in glioma and non-small-cell lung cancer (NSCLC); activation of the PI3K pathway may contribute to increased cell proliferation, migration and invasion." (PMID 30003082, 2018). "In vitro, hypoxia upregulated PLOD2 protein in U87 and U251 human glioma cell lines." (PMID 28423580, 2017). "Furthermore, immunohistochemical staining of PLOD2 protein was performed with 125 paraffin-embedded glioma samples and 30 normal brain tissues." (PMID 28410212, 2017). "However, little is known about the function and molecular mechanism of PLOD2 in hypoxia-induced glioma migration and invasion." (PMID 28410212, 2017).
glioma (continued). "Our study demonstrates that PLOD2 is a potential oncogene participating in glioma pathogenesis and PLOD2 suppression might be a potential therapeutic strategy for glioma." (PMID 28410212, 2017). "In this study, PLOD2 was found to be frequently up-regulated in glioma and could serve as an independent prognostic marker to identify patients with poor clinical outcome." (PMID 28410212, 2017). "Taken together, these data demonstrated that PLOD2 promoted tissue invasion of human glioma cells." (PMID 28423580, 2017). "The glioma tissues showed markedly overexpression of PLOD2 (P < 0.001)." (PMID 28410212, 2017). "When PLOD2 is inactivated, the ability of glioma cells to survive hypoxia condition might be weakened." (PMID 28410212, 2017). "Knockdown of PLOD2 partially inhibited hypoxia-mediated glioma cell migration and invasion." (PMID 28410212, 2017). "This is the first report to demonstrate the functional significance of PLOD2 in glioma." (PMID 28410212, 2017). "Taken together, PLOD2 mediated hypoxia-induced EMT in glioma cells." (PMID 28410212, 2017). "The role of PLOD2 in glioma migration and invasion was examined in vitro." (PMID 28423580, 2017). "However, whether HIF-1α increases PLOD2 expression by directly binding to HREs or whether PLOD2 is involved in hypoxia-mediated glioma tumorigenesis still remains unclear." (PMID 28410212, 2017). "Our data suggests that PLOD2 may be a potential therapeutic target for patients with glioma." (PMID 28410212, 2017). "Most importantly, we have found that PLOD2 may be a valuable prognostic marker of glioma." (PMID 28410212, 2017). "Mechanistically, inhibition of PLOD2 inactivated PI3K/AKT signaling pathway and thus regulated the expression of its downstream epithelial–mesenchymal transition (EMT)-associated regulators, including E-cadherin, vimentin, N-cadherin, β-catenin, snail and slug in glioma cells." (PMID 28410212, 2017). "Similar to the TCGA datasets, all 11 genes exhibited WHO grade-dependent expression in glioma samples, with 6 upregulated (LDHA, MIF, NAMPT, PGK1, SAT1, and PLOD2) and 5 downregulated genes (ALDOC, ABAT, ADCY2, GALNT13, and PDE8B)." (PMID 38989284, 2024). "Consistent with the changes in expression, patients with higher expression of LDHA, MIF, NAMPT, PGK1, SAT1, and PLOD2, and lower expression of ALDOC, ABAT, ADCY2, GALNT13, and PDE8B showed poorer survival rates in all glioma samples." (PMID 38989284, 2024). "PLOD2, Spp1, SPOCK1 and CRLF1 can also serve as new targets for anti-tumor microenvironment therapy of glioma." (PMID 36819132, 2023). "Studies showed that PLOD2 was mediated by HIF-1α, TGF-β, and microRNA-26a/b to promote the occurrence and development of gliomas." (PMID 35479581, 2022). "Results showed that expression level of E-cadherin and Claudin was increased, and that of N-cadherin, PLOD2, MMP2 and Snail was significantly decreased after SKA1 knockdown in glioma cells." (PMID 31827398, 2019). "Five glioma cell lines, including U251, U87, U118MG, A172 and SHG44, exhibited different levels of PLOD2 expression." (PMID 28410212, 2017). "Therefore, we investigated whether HIF-1α could regulate PLOD2 expression in glioma cells." (PMID 28410212, 2017). "PLOD2 mRNA was significantly overexpressed in glioblastoma compared to low-grade tumors based on the Oncomine datasets and REMBRANDT database for human gliomas." (PMID 28423580, 2017). "Taken together, our results demonstrate that PLOD2 mediates hypoxia-induced EMT, at least in part in glioma cells." (PMID 28410212, 2017). "Other indicators of EMT activation in glioma NS include MMP1, TIMP1 and PLOD2." (PMID 36231068, 2022). "Previous studies have revealed that PLOD2 and PLOD3 have predictive effects on the prognosis of glioma, we speculated that PLOD1 also influence the prognosis of glioma, although it has not been explored." (PMID 34040895, 2021).
glioma (continued). "Both PLOD2 and PLOD3 had been reported to be highly expressed in gliomas, while the prognostic value of PLOD1 remains to be further illustrated, so we want to investigate the PLOD1 expression in glioma and its clinical implication." (PMID 34040895, 2021). "Moreover, we have shown that PLOD2 is induced by HIF-1α and then mediates hypoxia-induced EMT and migration in glioma cells." (PMID 28410212, 2017). "Although altered PLOD2 expression was observed in glioblastoma, the biological functions of PLOD2 in glioma tumorigenesis and progression have not been well characterized." (PMID 28410212, 2017). "Analysis of PLOD2 mRNA expression from the Repository of Molecular Brain Neoplasia Data (REMBRANDT) database (N = 178), further showed that PLOD2 mRNA expression was significantly increased in GBM compared to lower grade gliomas and normal brain tissue." (PMID 29165393, 2017). "Moreover, PLOD2 could be induced by hypoxia-inducible factor-1α (HIF-1α) via hypoxia, thereby promoting hypoxia-induced EMT in glioma cells." (PMID 28410212, 2017). "Interestingly, our results reveal that PLOD2 is directly induced by HIF-1α through the HREs located within the PLOD2 promoter and therefore may mediate hypoxia-induced EMT in glioma cells." (PMID 28410212, 2017). "Therefore, we speculated that PLOD2, a critical factor that promotes collagen cross-linking and acts upstream of LOX, may also activate the FAK pathway, in order to promote cell invasion in glioma cells." (PMID 28423580, 2017). "Interestingly, the role of PLOD2 has been reported in fibrous diseases, but not in glioma." (PMID 28423580, 2017). "Here, our data revealed that knockdown of PLOD2 resulted in decreased level of p-PI3K, p-AKT, p-GSK-3β and β-catenin, implicating that inactivated PI3K/AKT signaling may be responsible for shPLOD2-mediated suppression of glioma cell proliferation, migration and invasion." (PMID 28410212, 2017). "Dysregulation of procollagen-lysine, 2-oxoglutarate 5-dioxygenase 2 (PLOD2) was observed in gliomas, but the specific role and molecular mechanism of PLOD2 in glioma have not been reported yet." (PMID 28410212, 2017).
sarcoma (21 papers, 2015 to 2024). A usually aggressive malignant neoplasm of the soft tissue or bone. "In sarcoma, increased expression of PLOD2 is associated with a more metastatic phenotype, and loss of HIF-1α and HIF-1α-dependent PLOD2 expression disrupts cell migration and pulmonary metastasis." (PMID 37490147, 2023). "Loss or enhanced expression of PLOD2 abolishes or restores, respectively, the metastatic potential of HIF1α-deficient tumors and human sarcomas typically display high HIF1α and PLOD2 expression in metastatic primary lesions." (PMID 36232732, 2022). "For instance, in HIF-1α-deficient human sarcoma, the expression of ectopic PLOD2 restored the potential of migration and metastasis, while inhibiting the activity of PLOD2 resulted in decreased tumor metastasis." (PMID 34944486, 2021). "Loss or overexpression of PLOD2 abrogates or restores, respectively, the metastatic potential of HIF1α-deficient tumors and human sarcomas show elevated HIF1α and PLOD2 expression in metastatic primary lesions." (PMID 34294128, 2021). "Hypoxia-induced expression of PLOD2 in sarcomas enhances collagen fiber size and tumor density and thus promotes lung metastasis." (PMID 37490147, 2023). "PLOD2 is overexpressed in various cancers such as oral carcinoma 12, glioblastoma 13, bladder cancer 14, bone metastasis 15, and sarcoma 16, and is correlated with a poor prognosis." (PMID 36632453, 2023). "Next, immune infiltration in sarcoma was analyzed by TIMER, and the results showed that the expression of PLOD2 in sarcoma was correlated with B cells, CD8 positive T cells, CD4 positive T cells, macrophages, neutrophils and DC cells." (PMID 36276118, 2022). "For example, PLOD2 was regulated by hypoxia-inducible factor-1α (HIF-1α) to promote sarcoma metastasis; PLOD2 was regulated by miRNA-26a-5p and miR-26b-5p in bladder cancer." (PMID 36276118, 2022). "Survival analysis by TIMER showed that the expression of CD4 positive T cells, Neutrophil and PLOD2 were related to the clinical prognosis of sarcoma patients." (PMID 36276118, 2022). "Comparison of RMS versus undifferentiated sarcomas in mice showed a significantly higher expression of PLOD2 in RMS (p = 0.044)." (PMID 33708626, 2021). "Previous studies have suggested that PLOD2 is overexpressed in sarcoma, bladder cancer, renal cell carcinoma, glioblastoma, cervical cancer, oral carcinoma, bone metastasis and other types of cancers." (PMID 31455288, 2019). "Additional studies have indicated that HIF-1α enhances expression of PLOD2, which in turn promotes sarcoma metastasis." (PMID 30563531, 2018). "An inhibitor of PLOD2 (minoxidil) can suppress sarcoma metastasis." (PMID 36632453, 2023). "In general, murine sarcomas with Rb1 nullizygosity were associated with the undifferentiated morphology, except for one case identified as aRMS which also showed lower expression of COL18A1, COL4A1, and PLOD2 compared to Rb1 wildtype sarcomas (p = 0.0035, 0.04, and 0.08, respectively)." (PMID 33708626, 2021). "Accumulating evidence indicates that PLOD2 is significantly overexpressed and related to poor prognosis of patients in several types of solid tumors, such as hepatocellular carcinoma, pancreatic cancer, sarcoma, and head and neck squamous cell carcinoma (HNSCC)." (PMID 34944486, 2021). "Indeed, mechanical (composition of the extracellular matrix) and chemical stress (hypoxia) increase the motility and capacity of sarcoma cells to metastasize, through increased expression of procollagen-lysine, 2-oxoglutarate 5-dioxygenase 2 (PLOD2), a collagen cross-linker." (PMID 31370265, 2019). "The Rb1 nullizygous sarcomas had a significantly lower number of tumors expressing COL18A1, COL4A1, and PLOD2." (PMID 33708626, 2021).
hepatocellular carcinoma (20 papers, 2014 to 2025). A malignant tumor that arises from hepatocytes. "Consistent with our results, PLOD2 overexpression has been reported to be associated with the clinical progression and poor outcome of patients with bladder cancer, hepatocellular carcinoma or glioblastoma." (PMID 28410212, 2017). "In addition, the incidence and growth of hepatocellular cancer was decreased in PLOD2-deficient mice compared with wild-type mice." (PMID 31446433, 2019). "However, apparent up-regulation of IGF-II, PAI-1 and PLOD2 was observed in melanoma-, lung adenocarcinoma- and multiple myeloma-associated fibroblasts, as well as in hepatocellular carcinoma-associated fibroblasts." (PMID 26029019, 2014). "Previous research showed that PLOD2 was highly expressed in various cancer types, including hepatocellular carcinoma (HCC), oral squamous cell carcinoma (OSCC), gastric cancer and lung cancer." (PMID 36276118, 2022). "This is different from that upregulation of the total PLOD2 is considered as an independent factor for poor prognosis in hepatocellular carcinoma." (PMID 34944486, 2021). "PLOD2 expression has been found to provide prognostic information about bladder cancer, hepatocellular carcinoma and glioblastoma." (PMID 28410212, 2017). "Up-regulation of PLOD2 has also been found in colorectal cancer, cervical cancer and hepatocellular carcinoma." (PMID 28410212, 2017). "PLOD family members (PLOD1, PLOD2, and PLOD3) were shown to be associated with poor prognosis and could act as potential biomarkers or therapeutic targets for both gastric cancer and hepatocellular carcinoma." (PMID 36820030, 2023). "Furthermore, very recent studies found a correlation between high tumor levels of PLOD2 and high neutrophil infiltration in cervical and hepatocellular carcinoma tissues." (PMID 35682709, 2022). "In hepatocellular carcinoma, PLOD2 expression correlated with aggressive progression; moreover, PLOD3 was found to be highly expressed in this cancer and may be a promising diagnostic biomarker." (PMID 31446433, 2019). "The PLOD2 expression is significantly correlated disease-free survival and tumor size in hepatocellular carcinoma (HCC)." (PMID 30003082, 2018). "PLOD2 was related to HNSCC, hepatitis C, hepatocellular carcinoma, renal cell carcinoma, and CTLA4 inhibitory signaling while PLOD3 was linked to basal cell carcinoma, renal cell carcinoma, ncRNAs involved in WNT signaling in hepatocellular carcinoma, and FRS-mediated FGFR2 signaling." (PMID 36820030, 2023).
bladder cancer (19 papers, 2017 to 2024). "Recent studies found that high levels of PLOD1 and PLOD3 were related to short OS in gastric cancer, and high levels of PLOD1 and PLOD2 were related to poor OS in bladder cancer." (PMID 39068670, 2024). "In bladder cancer, hsa-miR-26b prevents tumor migration and invasion by regulating the PLOD2 gene and it performs a similar function by targeting the SMAD1 gene in liver cancer." (PMID 36820950, 2023). "MiR-26a-5p and miR-26b-5p can regulate PLOD2, and PLOD2 is a potential prognostic marker for bladder cancer." (PMID 35912206, 2022). "FOXA1 has been documented to bind to the promoter of KDM6A and PLOD2, thus promoting their transcription in bladder cancer and non-small-cell lung cancer, respectively." (PMID 35498155, 2022). "PLOD2 is overexpressed in different cancers such as bladder cancer, renal cell carcinoma, and oral carcinoma, and is closely associated with poor prognosis." (PMID 34257533, 2021). "PLOD2 is also directly regulated by miR-26a-5p and miR-26b-5p, and PLOD2 expression is a potential prognostic marker for patients with bladder cancer and renal cell carcinoma." (PMID 30003082, 2018). "Furthermore, miR-26a-5p was found to be downregulated in bladder cancer and to inhibit cancer cell migration and invasion by repressing PLOD2." (PMID 39062049, 2024). "Although PLOD1 was proven to promote aggressiveness of bladder cancer cells, the potential roles of PLOD1 and PLOD2 in RCC were not elucidated." (PMID 33287763, 2020).